PCNA (proliferating cell nuclear antigen)
Diseases named in the same sentence as PCNA in open-access papers (continued):
Sharing a sentence is not in itself a finding about the gene and the disease.
tumor (continued). "Similarly, protein levels of PCNA, cyclin D1, cyclin E, and MMP-9 decreased, whereas TNFα expression increased in the tumor area of the HCT-116 xenograft in nude mice." (PMID 36979011, 2023). "A few studies of ESCC have found higher elafin protein expression in tumor nests with well-differentiated tumor cells, but not in highly proliferated PCNA-expressing tumor cells." (PMID 37568641, 2023). "Moreover, the expression of Gpx-1 was related to the expression of proliferating cell nuclear antigen (PCNA) which is commonly present in proliferating cells and tumour cells." (PMID 37242524, 2023). "The TMZ impact on PBT24 and SF8628 tumor PCNA expression was similarly significantly effective but did not alter EZH2 expression in the studied tumors." (PMID 35216113, 2022). "Moreover, analysis of tumor specimens from the AP-treated animals showed reduced expression of BCL2, cyclin B1, and PCNA (proliferating cell nuclear antigen) and increased Bax and Cip1/p21 expression." (PMID 35334790, 2022). "PCNA is a kind of nuclear protein that ubiquitously exists in normal proliferating cells and tumor cells." (PMID 35401213, 2022). "Proliferation markers such as KI67 and PCNA showed no differential expression between the three tumor lineages or between tumoral tissues and non-tumoral pituitaries." (PMID 35260162, 2022). "At the molecular level, ADE/GA-HA NPs reduced the expression of proliferating cell nuclear antigen (PCNA), an immunohistological marker for the in vivo evaluation of tumor growth, and increased apoptotic DNA fragmentation (TUNEL assay) when compared to other groups." (PMID 35335138, 2022). "PCNA and Ki-67 staining were lower in the CTX-INS-GNP-treated group than in the other two groups, indicating that the addition of the nanoparticles to standard of care therapy reduced tumor proliferation and tissue repair levels." (PMID 36324626, 2022). "Other intestinal stem cell markers and genes associated with proliferation, notably proliferating cell nuclear antigen (PCNA), prominin 1 (PROM1), HOP homeobox (HOPX), and olfactomedin 4 (OLFM4), were also increased in LPS-treated IBD intestinal organoids and tumor enteroids." (PMID 35884586, 2022). "Furthermore, in vivo assays showed that T4O had the potential to inhibit PC cell proliferation and decrease EMT biomarkers, KI67, PCNA and ROCK2 in tumor tissues." (PMID 35322742, 2022). "PCNA protein expression was significantly (p < 0.05) inhibited at a rate of 32% in the RTP-H treatment group compared to the tumor group, while the inhibitory effects were not significant (p > 0.05) in the RTP-L treatment group." (PMID 35269987, 2022). "LncRNA PCNAP1 is a pseudogene of PCNA highly expressed in HBV-positive HCC cells and tumor tissue." (PMID 36203765, 2022). "In the METABRIC Validation cohort, as for the Discovery cohort, the signatures Oncotype Dx, PCNA and Stathmin were significantly higher expressed in BC of the young compared to older women when not stratifying for tumour subtype." (PMID 35995935, 2022). "To address this point, we performed co‐immunostaining for PCNA (marker of cell proliferation), pan‐cytokeratin (Pan‐CK, highlighting tumor cells), and DAPI (for nuclei) in N = 2 POSTN‐high and N = 2 POSTN‐low PDX tumors and quantified PCNA expression in stromal and tumoral cells." (PMID 36102377, 2022). "Furthermore, the results from the subcutaneous xenograft model showed that knocking out CBX1 significantly inhibited tumor growth and that tumor tissues in the CBX1‐knockout group had lower expression of Ki67 and PCNA than those in the sgNC group." (PMID 36310139, 2022). "Expression of each of these proliferative markers (PCNA, MKI67, and HDAC1) positively correlated with that of KSR2, indicating KSR2 may promote tumor proliferation." (PMID 35468812, 2022).
tumor (continued). "PCNA protein expression was also significantly reduced in the CDDP treatment group compared to the tumor group, but this reduction was not significant (p > 0.05) when compared with the RTP-H treatment group." (PMID 35269987, 2022). "We also examined the protein level of tumor tissues in two groups, which showed that PHGDH and pathway-related indicators β-catenin, c-myc, cyclin D1, PCNA, Bcl2, N-cadherin, vimentin, and Snail expression level were lower and BAX and E-cadherin higher in CBR-5884 group." (PMID 36105480, 2022). "In addition, immunofluorescence staining using xenograft ccRCC tumor tissues showed increased localization of CX3CL1; GPX4 and PCNA were found to have decreased expression in the OE-CX3CL1 group compared to that in the control group." (PMID 36397015, 2022). "In this contribution, we particularly paid attention to the influence of the X-PDT on tumor migration and the results showed that X-PDT based on Cu-Cy NPs could inhibit tumor cell proliferation and migration via modulating PCNA and E-cadherin." (PMID 34466749, 2022). "The results showed that the masses consisted of only tumour tissue and that the tumours that were removed from mice injected with NCAPG-overexpressing cells had higher expression levels of NCAPG, PCNA, and Ki-67 than those removed from mice in the control group." (PMID 35864529, 2022). "Morphometric analysis of immunohistochemical images showed that RLS40 tumor tissue without treatment (control) and tumors injected with control oligonucleotide μ-Scr-ON has 66 ± 6.1% and 56.2 ± 8.3% of PCNA-positive cells, respectively." (PMID 36139555, 2022). "TUNEL staining of tumor tissues demonstrated that TTD induced apoptosis, and western blot analysis of tumor lysates showed that TTD decreased the protein level of PCNA and survivin and increased protein levels of GRP78 and CHOP." (PMID 35563670, 2022). "In accordance with the in vitro data, further detailed analysis of the tumor tissues revealed that the MDR1 and proliferating cell nuclear antigen (PCNA) protein levels were decreased, whereas the γH2AX and apoptosis protein Bcl2 levels were upregulated in the mouse tumors upon Gli2 knockdown." (PMID 35059317, 2021). "Neither tumor burden, as assessed by HE staining, nor tumor cell proliferation, as assessed by % proliferating cell nuclear antigen (PCNA)-positive cells within tumors, revealed significant differences between KPGEMM and KPCRISPR." (PMID 33738287, 2021). "PCNA and Ki67 immunostaining experiments confirmed that Probio-M9 administration suppressed the abnormal growth signal in tumor areas and accelerated mucosal repair in non-tumor areas." (PMID 33808480, 2021). "Moreover, the mice injected with shNAP1L1-U87 and shNAP1L1-LN229 cells exhibited lower expressions of Ki67, proliferating cell nuclear antigen (PCNA) and NAP1L1 in tumor tissues relative to the control mice." (PMID 34959221, 2021). "Histological analysis and immunohistochemical staining for Ki-67, ApopTag®, F4/80, CAE, and CD31, as well as protein expression of PCNA, caspase-3 and cleaved-caspase-3, were performed to study proliferation, apoptosis, inflammation, and angiogenesis in CAP-treated tumours." (PMID 34069689, 2021). "The data presented that PCNA, MMP2 and MMP9 were all strikingly downregulated in the sh-hsa_circ_0004712 experimental group compared to the sh-NC control group, while the level of C-caspase 3 was opposite to them, suggesting that tumor growth was inhibited." (PMID 34507595, 2021). "Consequently, we assessed the staining intensity of KI67, PCNA, VEGFA, and Caspase-3 in the tumor tissues using immunohistochemistry." (PMID 34544413, 2021).
tumor (continued). "Moreover, the levels of PCNA, VEGFR1 and VEGFR2 were reduced, indicating that JCo extract inhibited tumor proliferation and autocrine signaling." (PMID 34151367, 2021). "This process of BHRF1+/SNHG8 high/miR-512-5p low/TRIM28high in EBVaGC directly enhances the activation of a set of tumor-promoting factors, such as proliferation-related genes (BCL-2, CCND1, PCNA, PARP1) and metastasis-related genes (Snail, VIM, CDH1, and CDH2)." (PMID 34722282, 2021). "We found that PCNA and Ki‐67 were abundant in HIF‐1α MOCK fibroblasts tumour tissues." (PMID 33943003, 2021). "For example, the smaller cell cluster B4b was a highly proliferative tumor with cells at either the G2/M, or S phase (right two panels) and displayed high expression of MKI67, CDK4, and other proliferative markers such as PCNA, TK1, and TYMS." (PMID 34001881, 2021). "Therefore, HE staining and the expression of PCNA and CD34 were used to evaluate the infiltration degree and proliferation rate of tumor cells in the peripheral soft tissue of puncture passage." (PMID 33743772, 2021). "Markers of proliferation Ki-67 and PCNA were absent in non-tumour cells and strong nuclear staining was observed in few cells of the tumour tissue." (PMID 33906633, 2021). "The upregulated PCNA expression was also confirmed by western blotting with protein lysis from liver nontumor and tumor areas, although the difference was not statistically significant." (PMID 34876963, 2021). "Also, in vivo CERCAM silencing decreased the protein levels of PCNA and CERCAM in tumor tissues compared with those in the lv‐sh‐NC group." (PMID 34105305, 2021). "The combination of PCNA and CD34 can reflect the proliferation of tumor." (PMID 33743772, 2021). "During tumor transformation, these proteins can be transported to the surface of tumor cells, leading to NK cell activation upon binding to 21spe-MML5, whereas binding to PCNA inhibits NK cell effector function." (PMID 34572949, 2021). "The spatiotemporal patterns of changes in ADC were similar in both U87 and U251 tumors as ADC was higher at the periphery regardless of tumor size, as supported by PCNA IHC data with increased PCNA staining at the tumor margins." (PMID 34513675, 2021). "Lycopene supplementation (1, 20 mg/kg BW; 2 times per week for 12 weeks) in nude mice injected with SK-Hep-1 cells managed to significantly reduce MMP-2, VEGF, PCNA, MMP-9, suppress tumor metastasis, mean number of tumors, tumor cross-sectional area while increase nm23-H1." (PMID 34202203, 2021). "PDAC cell lines that overexpressed PRLR-SF formed significantly smaller xenograft tumors in mice (based on the tumor weights) than PDAC cells transduced with a control vector and had a lower proliferation index (based on staining for proliferating cell nuclear antigen)." (PMID 33664869, 2021). "Furthermore, IHC staining demonstrated that knockdown of circSEC24A remarkably reduced the expression of Ki-67, PCNA and TGFBR2 in xenograft tumor tissues." (PMID 34906151, 2021). "Finally, we performed HE staining, immunofluorescence staining, immunohistochemical staining, and Western blot analysis on nude mouse tumor tissues to detect protein expression changes in HK2, GLUT1, Ki67, PCNA, CDK2, CyclinD1, Bax, and Bcl-2." (PMID 34893086, 2021). "Tumor growth, blood lymphocyte levels, cell cycle progression, apoptosis, apoptotic regulator expression, TNF-α expression, changes in mitochondrial membrane potential (MMP), PCNA, and CD4+ and CD8+ T cells in tumor cells were quantitatively evaluated by flow cytometry or RT-PCR." (PMID 32345289, 2020). "With the higher intake of nano-LSW, the expression of PCNA, HMGB1 and other related tumor proliferation and migration factors in cells may be altered." (PMID 32754037, 2020). "Finally, the proliferation marker PCNA and the invasion marker MMP2 were detected by IHC staining in tumor xenografts." (PMID 33093458, 2020).
tumor (continued). "Furthermore, we investigated the changes in the expression of multiple critical factors (including COX-2, TNF-α, β-catenin, HMGB1, PCNA, PPAR-γ, AP-2, Smad-2, TGF-β1) for the tumor microenvironment after treatment with nanoparticle-encapsulated LSW." (PMID 32754037, 2020). "We also found inhibition of P38 phosphorylation and reduced PCNA, Ki67 and BCL2 levels, suggesting that the anti-inflammatory effects of GP inhibits P38, acting as an upstream regulator to inhibit proliferation and reduce tumor cell survival." (PMID 32630288, 2020). "Similarly, the tumor cell tissues with higher proliferation (such as colon epithelium) showed induction of both γH2AX and IGF1R/PCNA." (PMID 32701997, 2020). "Similarly, PCNA-mRNA-expression significantly increased in human liver scaffolds engrafted with HepG2 and LX2-cells, compared to those engrafted with only tumor cells." (PMID 33103995, 2020). "Finally, the tumor suppressor activity of P21 can be promoted by interaction with tumor-related factors like MYC, proliferating cell nuclear antigen (PCNA), and signal transducer and activator of transcription (STAT3)." (PMID 31998417, 2020). "We show that APE2 mRNA expression is positively correlated with PCNA, APE1, XRCC1, PARP1, Chk1, and Chk2 across these 6 tumor tissue types; however, groupings of other DNA repair and DDR genes are correlated with APE2 with different patterns in different cancer types." (PMID 32111912, 2020). "In particular, on tumor cells, NCRs may recognize intracellularly localized proteins, such as BAT3/BAG6 and PCNA, that may be expressed at the cell surface of stressed or cancer cells, or cell surface molecules, such as B7-H6 and 21spe-MLL5." (PMID 33321719, 2020). "Proteins from transplanted tumor tissues were extracted for Western blot analysis, and the results displayed that levels of FTO, MYC, CDK2, CDK4, Ki-67, PCNA and Bcl-2 proteins in miR-96 antagomir group were downregulated, while AMPKα2 and Bax proteins were raised." (PMID 33183350, 2020). "Moreover, immunohistochemistry assay revealed that downregulation of SEMA3F countervailed the effect of FAM83C-AS1 sponging on the expression of Ki67, PCNA, E-cadherin and N-cadherin, indicating that SEMA3F depletion promoted tumor growth and EMT process." (PMID 33109776, 2020). "Tumor HIF-1α, CAIX, Ki67, and PCNA amounts were continuously down-regulated during radiotherapy." (PMID 32766135, 2020). "Results from an immunohistochemistry assay showed that hMBSCs significantly decreased the positive rates of PCNA in the HeLa/hMBSC-coinjected tumor tissues compared with those in the HeLa cells alone tissues and HeLa/NIH 3T3-coinjected tumor tissues, which was consistent with the in vitro results." (PMID 31236116, 2019). "Furthermore, Rk1 treatment reduced the proliferation markers such as Ki-67 and PCNA but also increased the apoptotic markers such as TUNEL and cleaved caspase-3 in the Rk1-treated tumor tissues." (PMID 30862004, 2019). "Ligands for NKp44 have been identified during pathological conditions such as tumor development or immortalized cell lines of cancerous origin, and include an isoform of the protein MLL5, proliferating cell nuclear antigen (PCNA), and platelet derived growth factor (PDGF)-DD." (PMID 30984202, 2019). "Further, it showed down-regulation of PCNA and GLUT1 proteins in excised xenograft tumor tissues." (PMID 30875788, 2019).
tumor (continued). "Proliferating cell nuclear antigen (PCNA) is a nuclear marker known to reflect cell turnover and may be used as a marker for tumour aggressiveness." (PMID 31672124, 2019). "Additionally, overexpression of circGRAMD1B triggered a reduction of Ki-67, PCNA, and Vimentin expression, while an increase of circGRAMD1B, PTEN, p21, and E-cadherin mRNA level in excised tumor masses." (PMID 31719211, 2019). "Additionally, the PCNA‐positive cells were elevated in NDEA group, indicating accelerated proliferation of tumor cells." (PMID 31428352, 2019). "(C) Immunohistochemical analysis of TRIAP1, PCNA and CAV1 in isolated PC3 xenograft tumours." (PMID 30871022, 2019). "For in vivo experiments, a xenograft model where OSCC cells stably expressing ADAR1 were implanted was used to investigate the effect of ADAR1 on tumor growth and progression, and the expression of ADAR1, PCNA, SOX2 and POU5F1 was further detected by immunohistochemistry." (PMID 31315644, 2019). "PCNA is one of the markers of cell proliferation, which is upregulated in tumor cells, thus we evaluated if VERU-111 treatment inhibits PCNA expression in tumor tissues." (PMID 30674344, 2019). "PCNA and VEGF are related to cell proliferation, metastasis, and invasion of the tumor cells." (PMID 29808160, 2018). "The p21 protein (also known as WAF1 or CIP1) was initially documented to be a tumor suppressor protein due to its ability to inhibit cyclin-dependent kinase (CDK) and proliferating cell nuclear antigen (PCNA) functions, finally contributing to cell cycle arrest." (PMID 30304835, 2018). "In one study, analysis of the expression of PCNA was also confirmed in non-neoplastic, adjacent tissues, suggesting the presence of early micrometastases and higher tumor aggressiveness, which was histologically confirmed." (PMID 30373614, 2018). "Consistent with our short-term findings, HCC tumor tissue and matching paracancerous tissue in long-term DEN-treated CCR10 KO mice displayed significantly lowered hepatocellular Akt phosphorylation and PCNA expression." (PMID 29445190, 2018). "We characterized one potential peptide, NKp44-derived pep8 (NKp44-pep8), which manifested a specific interaction with PCNA and blocked NKp44 binding to PCNA; upon fusion to cell-penetrating peptide (CPP), pep8 induced tumor cell death in vitro as well as tumor growth suppression in vivo." (PMID 29875773, 2018). "Subcutaneous tumor paraffin section IHC results showed that PCNA staining in the FSTL5 group and control group were not significantly different (n = 3), and FSTL5 upregulated levels of Cleaved Caspase‐3." (PMID 30255547, 2018). "Many of these genes, including those encoding bFGF, MAPK10, MAP3K5, IL1R2, E-cadherin, Ki67, Cyclin E1, beta-catenin, 14-3-3 protein T-cell (YWHAQ), integrin alpha-V (ITGAV), integrin alpha-10 (ITGA10), CDK6, PCNA, CDKN1A, and PAK3, are related to tumor metastasis and regulation of cell migration." (PMID 28454092, 2017). "YAP promoted the expression of PCNA and Cyclin-D3, whereas 14-3-3ζ inhibited their expression Western blot and immunofluorescence assays revealed that 14-3-3ζ overexpression increased the phosphorylation of YAP at the Ser127 site in subcutaneous tumor tissue." (PMID 29069755, 2017). "To test whether reduction of granzyme B+ cells correlate with changes in tumor antigen load in TLO from advanced and evanescent carcinoma patients, we stained prostate sections with antibodies against PCNA, PSCA, and plasma cell antigen." (PMID 28567040, 2017). "Nevertheless, treatment of gefitinib, erlotinib, or MTE alone did not exert significant changes in expression of PCNA, cell apoptosis, or tumor angiogenesis." (PMID 28915640, 2017). "The DTX-LP group had weaker PCNA and CD31 signals compared to the DTX-IN groups, suggesting that lung-targeted liposomes successfully delivered DTX to the lung tumor tissue to inhibit tumor growth, reduce tumor mass and enhance antitumor effects." (PMID 28855665, 2017).